BRCA1 (BRCA1 DNA repair associated)
Diseases named in the same sentence as BRCA1 in open-access papers (continued):
Sharing a sentence is not in itself a finding about the gene and the disease.
ovarian carcinoma (continued). "Experiments have demonstrated that BRCA1 promoter methylation defects have been detected in some OC ovarian cancer samples." (PMID 36091750, 2022). "This was the first study in Vietnam to investigate mutations of BRCA1 and BRCA2 genes in breast and ovarian cancer patients with the criteria of HBOC syndrome, and to develop a risk score associated with the cohort based on carrier status and family history." (PMID 35205313, 2022). "McLeavy and colleagues found that patients with ovarian cancer who underwent mainstreamed genetic testing for the BRCA1 and BRCA2 genes reported low levels of decision regret, uncertainty, or lack of control following their test." (PMID 35621678, 2022). "The success of PARPi therapy in BRCA1/2 defected breast and ovarian cancer attracts great interests in exploring its potential to treat other cancer types with BRCAness features." (PMID 36497135, 2022). "For women with BRCA1 and BRCA2 mutations, oral contraceptive use reduces the risk of ovarian cancer by 50% with a further 36% risk reduction for each additional 10 years of use." (PMID 35159349, 2022). "In 1990, a geneticist, Mary-Claire King discovered the BRCA1 gene locus and its linkage to hereditary breast and ovarian cancer." (PMID 36284291, 2022). "Consistent with the results above, when BRCA1 was knocked down in BRCA1 wide-type ovarian cancer cell lines, the cells expressed higher levels of ADRB1, which promoted the production of cAMP." (PMID 35517499, 2022). "This has led to a significant progress for identification of the genes which are found in people with greater chances of development of ovarian carcinoma (for example, the BRCA1 and BRCA2)." (PMID 36415372, 2022). "Our results found that, ovarian cancer cells treated with Cur + PTX + si-BRCA1 showed higher cell viability, proliferation rate, colony formation and EdU incorporation rate than cells treated with Cur + PTX + si-NC." (PMID 36703740, 2022). "This study retrospectively analysed the results of screening for genetic mutations of the BRCA1 and BRCA2 in breast and ovarian cancer patients among this population." (PMID 35918668, 2022). "Since then, evidence for this has accumulated and a salpingectomy for the prevention of ovarian cancer among BRCA1/2-PV carriers was proposed." (PMID 34997316, 2022). "The HR mechanism is usually associated with cancer and BRCA1 and BRCA2 mutations, which are linked to hereditary breast and ovarian cancer." (PMID 36499000, 2022). "Females that carry germline BRCA1 or BRCA2 pathogenic variants are at high lifetime risk of breast and ovarian cancer diagnoses, which can be 70% and 44%, respectively." (PMID 36358902, 2022). "Analysis of 299 ovarian cancer samples from The Cancer Genome Atlas (TCGA) confirmed the coordinated expression of BRCA1/2 and HR genes." (PMID 35203410, 2022). "Methylation of the BRCA1 promoter that silences BRCA1 gene expression has been reported in ovarian cancer tissue." (PMID 36230543, 2022). "Promoter methylation plays important roles in de-regulation of BRCA1/2 expression in breast and ovarian cancer." (PMID 36497135, 2022). "In the context of ovarian cancer, such tumor suppressor genes included BRCA1, RASSF1A, E-cadherin (CDH1), HIC1, APC and the HOX genes, among others." (PMID 35740550, 2022). "Monoallelic pathogenic variants in FANCD1/BRCA2, FANCS/BRCA1, FANCJ/BRIP1, FANCM, FANCN/PALB2, and FANCO/RAD51C have been linked to familial breast and ovarian cancer." (PMID 36428697, 2022).
ovarian carcinoma (continued). "Promoter silencing of the HR genes, including BRCA1 and RAD51C, has been detected in ovarian cancers associated with HRD phenotypes, and this is one of the major causes of gene inactivation." (PMID 35626108, 2022). "Since then, the risks for breast and ovarian cancer in BRCA1/2 PV carriers have been well characterized." (PMID 36497436, 2022). "It was first approved by FDA in 2016 for somatic and germline BRCA1/2m advanced ovarian carcinomas in patients following multiple chemotherapy trials." (PMID 36533080, 2022). "The BRCA1 p.(His1686Arg) variant was annotated as pathogenic in LOVD and ClinVar repository (VCV000584509.3) in association with several patients with BC and ovarian cancer." (PMID 36741700, 2022). "There are plenty of well-established PVs in ovarian cancer that have been shown to have a significant correlation with EOC such as BRCA1 and BRCA2." (PMID 35805770, 2022). "Transfection with let-7e sensitized epithelial ovarian cancer cells to cisplatin, down-regulated BRCA1 and RAD51 expression, and repressed the repair of cisplatin-induced DSBs." (PMID 35328651, 2022). "In search of genetic factors that affect cancer risks in BRCA carriers, we carried out the first whole-genome sequencing study in a unique registry of familial ovarian cancer, selected to enrich with BRCA1/2 carriers." (PMID 35625955, 2022). "We found that expression of ADRB1 in BRCA1-defective ovarian cancer cells was activated by extracellular catecholamine hormones." (PMID 35517499, 2022). "The initially described alterations involved BRCA1 and BRCA2 pathogenic variants (PVs), found in about 20–30% of ovarian cancers at diagnosis, urging the development of PARPi." (PMID 35158866, 2022). "A Hong Kong study of 1,236 patients with high-risk hereditary breast and/or ovarian cancers showed that, among 120 deleterious BRCA mutations, 8 (6.7%) were LGRs involving BRCA1 (5/57, or 8.8%) and BRCA2 (3/63, or 4.8%)." (PMID 35924163, 2022). "Carriers of germline mutations in BRCA1 and BRCA2 genes have a lifetime risk of ovarian cancer of 35–60% and 12–25%, respectively, along with an increased risk of peritoneal and fallopian tube malignancies." (PMID 35805770, 2022). "Germline pathogenic variants in BRCA1/2 have been established in hereditary breast and ovarian cancer (HBOC) syndrome and result in significantly elevated lifetime risk of ovarian cancer." (PMID 35768821, 2022). "A recent study examined the impact of reduced BRCA1 expression on metabolic reprogramming of ovarian cancer cells." (PMID 35432218, 2022). "The major clinicopathological characteristics, BRCA1/2, and other HRR gene mutations in epithelial ovarian cancers." (PMID 35186721, 2022). "Beyond germline BRCA1/2 mutations, a small percentage of BRCA-related ovarian cancers harbor somatic mutations." (PMID 35813356, 2022). "While pathogenic mutations in genes such as BRCA1 and BRCA2 confer high risks of breast and ovarian cancers, these account for only a small proportion of all cancer cases in the general population." (PMID 35877228, 2022). "BRCA1/2 defects are present in about 5% of breast cancer and 20% of ovarian cancer patients, which are the major beneficiaries for the PARP inhibitor therapy." (PMID 36497135, 2022). "Q1756fs*74 in BRCA1 gene was also observed in Italian, Israel, USA, Brazilian, Ukrainian, Polish and Czech population with familial breast and ovarian cancer." (PMID 35753294, 2022). "For instance, it is well established that monoallelic mutations in FANCS/BRCA1 and/or FANCD1/BRCA2 are associated with breast and ovarian cancer susceptibility." (PMID 35330396, 2022). "How to improve the therapeutic effects of PARP inhibitor in BRCA1/2-proficient ovarian cancers is still an urgent problem needed to be solved at this stage." (PMID 36267463, 2022).
ovarian carcinoma (continued). "This protective effect was also recently reported with BRCA1/2 carriers to be a 76% reduction in ovarian cancer after >10 years of oral contraceptive use and persisted for >15 years." (PMID 35453839, 2022). "Recently, we found that pathogenic founder/recurrent germline mutations in 4 genes (BRCA1, BRCA2, RAD51C, PALB2) are responsible for 12.5% of ovarian cancer cases among unselected patients in the Polish population." (PMID 35313928, 2022). "Rising awareness about the importance of the BRCA1/2 genetic testing among Tunisian patients with a strong family history of breast and/or ovarian cancer will eventually lead to early disease detection." (PMID 36094928, 2022). "We also reported for the first time that Cur and PTX combination decreased the expression of miR-9-5p, thus improving BRCA1 levels in ovarian cancer cells." (PMID 36703740, 2022). "BRCA1, a tumor suppressor protein of breast and ovarian cancer, binds to a RING finger protein BARD1 to form a ring heterodimer and it functions as an E3 ubiquitin ligase for ubiquitination." (PMID 35265070, 2022). "To date, no studies have evaluated psychological outcomes following reflex tumour BRCA1/2 genetic testing among newly diagnosed ovarian cancer patients." (PMID 35418215, 2022). "The National Comprehensive Cancer Network and other guidelines recommend breast and ovarian cancer screening for BRCA1/2 carriers and prostate cancer screening particularly for BRCA2 carriers." (PMID 35077220, 2022). "It is opposite to the results of our study where the ovarian cancer onset for both BRCA1 and BRCA2 patients was soon after 40 years." (PMID 35469032, 2022). "BRCA1 and BRCA2 are the most well-studied and established genes in hereditary breast and ovarian cancer, while pathogenic variants in these genes are inherited in an autosomal dominant manner." (PMID 36358902, 2022). "In our study, we aim to explore levels of cancer worry and the course of cancer worry in BRCA1/2-PV carriers undergoing surgery to prevent ovarian cancer." (PMID 34997316, 2022). "BRCA1 and BRCA2 are the most studied BC susceptibility genes that explain a significant proportion of both hereditary breast and ovarian cancers." (PMID 36553480, 2022). "While the implication of BRCA1/2 genes in familial breast and ovarian cancer is widely understood, their role in the sporadic form of both cancers is still controversial." (PMID 35986351, 2022). "Recently, 21 founder and recurrent mutations in BRCA1/2, PALB2, RAD51C, and CHEK2 genes have been analyzed in a large Polish case-control study including 2270 ovarian cancer patients and 1743 controls." (PMID 35313928, 2022). "In the Australian Ovarian Cancer Study Group analysis, the OS and PFS of the patients with BRCA1/2 mutations in the germline were higher than in those patients without these genetic alterations." (PMID 35267543, 2022). "Inherited germline mutations in the breast cancer gene 1 (BRCA1) or BRCA2 genes (herein BRCA1/2) greatly increase the risk of breast and ovarian cancer, presumably by elevating somatic mutational errors as a consequence of deficient DNA repair." (PMID 35025760, 2022). "For example, preclinical studies demonstrate synergy between PARP inhibition and anti-CTLA-4 therapy in BRCA1/2 mutant ovarian cancer." (PMID 35626165, 2022). "We used the HR-competent cell lines SKOV3 and OVCAR3 to further investigate the combinatorial effects of DFMO, rucaparib, and cisplatin in ovarian cancer cells with wild-type BRCA1/2 functionality." (PMID 35736348, 2022). "In vitro and in vivo experiments demonstrated increased sensitivity to ionizing radiation in ovarian cancer cells carrying defective BRCA1, with data suggesting a role of BRCA1 in Foxp3 mediated radiation resistance." (PMID 36010882, 2022). "Mutations in BRCA1 and the BRCA1-associated ring domain protein (BARD1) make carriers more likely to develop breast and ovarian cancers." (PMID 36104717, 2022).
ovarian carcinoma (continued). "Hereditary breast and ovarian cancer (HBOC) syndrome is defined as an increased predisposition to breast and/or ovarian cancer, and 24% of families with HBOC were associated with the germline pathogenic variants in the BRCA1/2." (PMID 36463302, 2022). "Knocking out PPARGC1A in breast or ovarian cancer mouse models with mutated BRCA1/2 will also help to investigate the effect of PPARGC1A in increasing cancer risk in the context of BRCA1/2 mutations and to reveal the underlying biological mechanism." (PMID 35625955, 2022). "Germline mutations in both BRCA1 and BRCA2 can, therefore, lead to a deficiency in the HR pathway and increase susceptibility to ovarian cancer." (PMID 35805770, 2022). "This study is being repeated in BRCA1/2 carriers specifically at our dedicated familial ovarian cancer-reduction clinic to determine if the findings are reproduceable in a controlled surgical setting among carriers." (PMID 35323372, 2022). "Hereditary breast and ovarian cancers result mainly from inherited mutations in HRR genes, when the most common inherited mutations are in BRCA1 or BRCA2 genes." (PMID 36231059, 2022). "YHP-836 in UWB1.289, a BRCA1-null human ovarian cancer cell, was much more sensitive than this cell-restored wildtype BRCA1 (UWB1.289 + BRCA1)." (PMID 35910366, 2022). "Relatively little is known about reproductive decision-making in women harboring mutations in the BRCA1 and/or BRCA2—pathogenic variants that confer different cancer risk profiles and underlie hereditary breast and ovarian cancer." (PMID 35326645, 2022). "Several studies have examined the uptake of genetic testing for a germline BRCA1 or BRCA2 mutation for breast and ovarian cancer patients." (PMID 36547149, 2022). "In this study, by analysis of transcriptome data of ovarian cancer patients bearing BRCA1 defects in TCGA database, we found that cAMP signaling pathway was significantly activated." (PMID 35517499, 2022). "Inactivation of the breast cancer susceptibility gene 1 (BRCA1) plays a significant role in breast and ovarian cancers and qRT-PCR analyses indicated that KSRP was over-expressed in BRCA1 mutated tumors." (PMID 35563788, 2022). "About 3–10% of BRCA1/2 mutation carriers who undergo BSO are diagnosed with occult fallopian tube and ovarian cancers." (PMID 35267543, 2022). "When BRCA1 was knocked down in ovarian cancer cell lines bearing wide-type BRCA1, the expression of ADRB1 was significantly increased." (PMID 35517499, 2022). "Considering the 250 ovarian carcinoma with HRDsum ≥ 42, larger proportions of 27% and 18% had BA deleterious BRCA1/2 alterations and BRCA1-hypermethylated promoters, while the proportion of tumors in the other mutation classes was lower." (PMID 35681079, 2022). "It has been demonstrated that BRCA1 deficiency drives metabolic reprogramming by upregulating nicotinamide N-methyltransferase (NNMT), sensitizing ovarian cancer cells to agents that inhibit energy metabolism." (PMID 36230683, 2022). "Mutations in BRCA1 and PALB2 were associated with a high risk of ovarian cancer G1 (OR=8.53, p=0.005 and OR=7.03, p=0.03, respectively) and were related to worse all-cause survival for BRCA1 carriers (HR=4.73, 95%CI 1.45–15.43, p=0.01)." (PMID 35313928, 2022). "This study evaluated the preclinical efficacy of STS in combination with niraparib in the chemotherapy of BRCA1 wild-type ovarian cancer cells." (PMID 35016681, 2022). "On the other hand, we also detected the mRNA levels of DKK1 in BRCA1 knock-down ovarian cancer cell lines." (PMID 35517499, 2022). "BARD1, as a BRCA1 heterodimer interactor that plays an essential role as a tumor suppressor gene altered in breast and ovarian cancers, was also found to display a BRCA1-independent function during cancer progression." (PMID 35650591, 2022).
ovarian carcinoma (continued). "Defects in the HR pathway have been highlighted, mostly with loss-of-function mutations of BRCA1 and BRCA2, as germline mutations of these genes are significant risk factors for hereditary breast and ovarian cancers." (PMID 35163621, 2022). "In this study, by analyzing the transcriptome data from TCGA database, we found that cAMP signaling pathway was significantly activated in BRCA1-defective ovarian cancer patients." (PMID 35517499, 2022). "BRCA1 and BRCA2 are foundational to the HRR pathway and were initially discovered due to their association with hereditary breast and ovarian cancers." (PMID 35643464, 2022). "Clinical studies have shown that olaparib significantly prolongs the PFS in BRCA1/2 mutant ovarian cancer patients during both first-line maintenance therapy and platinum-sensitive relapse (PSR) maintenance treatment." (PMID 36034834, 2022). "The cause of ovarian cancer is not well known, but there are relations between mutated BRCA1 and BRCA2 genes (genes which help in repair of DNA) and occurrence of ovarian cancer." (PMID 35877745, 2022). "In fact, lessons learned from molecular and genetic analyses of BRCA1 transcended the area of familial breast and ovarian cancer and are regarded as universal biological paradigms in cancer." (PMID 35432218, 2022). "BRCA1 and BRCA2 mutations are known to contribute to the susceptibility of breast and ovarian cancers." (PMID 35740092, 2022). "BRCA1 and BRCA2 are the most frequently mutated genes in ovarian cancer (OC) crucial both for the identification of cancer predisposition and therapeutic choices." (PMID 36555431, 2022). "Germline mutations in breast cancer susceptibility gene 1 (BRCA1) and/or breast cancer susceptibility gene 2 (BRCA2) confer an increased risk of breast and ovarian cancers." (PMID 35918668, 2022). "Of the 240 ovarian cancer patients, 60 carried a BRCA mutation (43 patients (72%) with a BRCA1 mutation and 17 patients (28%) with a BRCA2 mutation)." (PMID 35409996, 2022). "Olaparib (Lynparza) was the first drug to be approved in 2014 by EMA and FDA in clinical use as monotherapy for the treatment of advanced germline BRCA1/2m ovarian cancer." (PMID 36533080, 2022). "There were 22 ovarian cancer patients with pathogenic variants, 3 with likely pathogenic variants, and 16 with VUS in the BRCA1 gene." (PMID 35918668, 2022). "Clinical BRCA1 and BRCA2 testing enables the identification of individuals at elevated risk for hereditary breast and ovarian cancer." (PMID 35918668, 2022). "For example, Chowdhury and colleagues have utilized a CRISPR‐Cas9 KO library to identify genes whose loss confers resistance to clinical PARP inhibition and to platinum‐based chemotherapy agents in BRCA1 null patient‐derived ovarian cancer cell lines." (PMID 35834102, 2022). "BRCA1 and BRCA2 are the most commonly mutated BC susceptibility genes that convey a high-risk of breast and ovarian cancer and represent 25%–28% of hereditary BC." (PMID 36003761, 2022). "An example of this is the identification of an ovarian cancer cluster region (OCCR) in or near exon 11 in BRCA1 and BRCA2." (PMID 35267543, 2022). "Determination of the BRCA1/BRCA2 mutation status in patients with breast and/or ovarian cancer is commonly performed using various molecular techniques." (PMID 35300046, 2022). "Carriers of pathogenic variants in BRCA1 or BRCA2 are at significantly increased risk (Relative Risk (RR) > 4) for breast and ovarian cancer and this knowledge can guide screening for early detection and the use of risk-reducing prophylactic surgeries." (PMID 35665744, 2022). "It is estimated that one-fifth of ovarian cancers are hereditary in origin, with BRCA1 and BRCA2 genes being the largest contributor." (PMID 35877228, 2022). "The assessment of BRCA1 status in hereditary breast and ovarian cancer patients is long established in the clinical routine to assist patients in prevention and treatment." (PMID 35837282, 2022).